CCND1 (cyclin D1)
Diseases named in the same sentence as CCND1 in open-access papers (continued):
Sharing a sentence is not in itself a finding about the gene and the disease.
melanoma (continued). "The ribociclib and binimetinib combination has demonstrated effectiveness in NRAS‐mutated melanoma, especially in patients with additional cell cycle gene mutations (CDKN2A, CDK4, and CCND1), who may derive greater benefit from this therapy." (PMID 39564955, 2024). "It has been found that the administration of lupeol has produced a dose-dependent reduction in the levels of β-catenin and WNT target genes, namely coding the region determinant-binding protein (CRD-BP), MITF and CCND1, which was in contradiction to Mel 1011 melanoma cells." (PMID 39684513, 2024). "In the present study, we focused on melanoma as a proof of concept and identified a lead molecule that could interfere with Bcl-3-mediated cyclin D1 expression as well as proliferation and migration in melanoma cells." (PMID 38238702, 2024). "In melanoma, p16CDKN2A is inactivated and CCND1 amplificated due to various epi/genetic mechanisms." (PMID 36676131, 2023). "Alternatively, 105 untransfected DCs were cultured with peptide pools (5μg/ml) from VSV, hTERT (melanoma antigen), Cyclin D1 (melanoma antigen), or the peptide SIINFEKL (irrelevant antigen) for 24 hours and then 106 purified CD8+ T cells were added in interferon gamma ELISPOT wells." (PMID 38022659, 2023). "Mutations resulting in constitutively active B-Raf proto-oncogene, serine/threonine kinase (BRAF) or NRAS proto-oncogene, GTPase (NRAS) proteins, which result in increased ERK kinase activity and, ultimately, CCND1 production, comprise 50% and 20% of all melanoma cases, respectively." (PMID 36696495, 2023). "In addition, we demonstrated that MTAP-ANRIL enhanced melanoma cell proliferation by upregulating the expression of the cell cycle regulators, cyclin B1 and cyclin D1." (PMID 37277447, 2023). "Previous studies showed that cyclin D1 overexpression might be sufficient to render BRAFV600E melanoma cells resistant to vemurafenib." (PMID 36210843, 2022). "In light of the previously-reported correlation between TMB and immune activity in the tumor microenvironment, we sought to determine whether there was a correlation between TMB and CCND1 amplification in melanoma using data from the MSKCC-IO cohort." (PMID 35844619, 2022). "Furthermore, we successfully established mice models of melanoma with a CCND1 amplification which recreated a similar immunosuppressive microenvironment." (PMID 35844619, 2022). "CCND1 is defined as an oncogene amplified in several tumors including melanoma." (PMID 36210843, 2022). "Finally, we analyzed the prevalence of TME-related angiogenesis molecules in melanoma with CCND1 amplification using data from the TCGA database." (PMID 35844619, 2022). "The evidence that approximately 20–38% of melanoma show CCND1 amplification, thus potentially being primarily resistant to BRAFi, has suggested that adding a CDK4/6 inhibitor could enhance the efficacy of BRAFi and MEKi." (PMID 36077374, 2022). "In addition, our study also identified aberrantly activated lipid metabolism in melanoma with CCND1 amplification." (PMID 35844619, 2022). "In this study, we explored the profile of melanoma with CCND1 amplification." (PMID 35844619, 2022). "Another key molecule of melanoma is the cell cycle regulator Cyclin D1, which has been demonstrated as an oncogene in cutaneous melanoma, and it could affect tumorigenesis via nuclear trafficking by multiple mechanisms." (PMID 36387162, 2022). "This was further demonstrated in a study that showed overexpressing cyclin D1 in a melanoma cell line could promote BRAF inhibitor resistance." (PMID 35525274, 2022).
melanoma (continued). "We believe the definition of CCND1 amplification as a unique genomic melanoma subtype, and application of genotype-specific treatments, offers a promising direction for the development of therapeutic strategies for treating melanoma patients with CCND1 amplification." (PMID 35844619, 2022). "According to previous studies, the roles of Cyclin D1 in melanoma cells are debatable." (PMID 36387162, 2022). "CCND1/cyclin D1 upregulation has been reported to be associated with reduced survival and lack of response to antitumor treatment in melanoma." (PMID 33804108, 2021). "Future studies assessing the prognostic and clinicopathological significance of CCND1/cyclin D1 in melanomas should consider the potential biases reported in the present systematic review and meta-analysis, using the QUIPS tool to improve the validity of findings and facilitating comparisons." (PMID 33804108, 2021). "Two studies analyzed both CCND1/cyclin D1 alterations (118 melanomas)." (PMID 33804108, 2021). "In malignant melanoma, the role of cyclins and especially cyclin D1 and D3 are well described." (PMID 33917849, 2021). "As results showed, PTEN and CCND1 might serve as key targets in correlation with melanoma metastasis." (PMID 33897771, 2021). "Future somatic copy number alteration bioinformatics analyses are needed in melanomas in order to comprehensively describe the genomic aberrations located in 11q13 chromosomal band—and singularly CCND1 amplification—from large-scale sequencing-based datasets (e.g., TCGA and ICGC projects)." (PMID 33804108, 2021). "The other three key genes, UBC, PTEN, and CCND1, were also well studied in melanoma." (PMID 33897771, 2021). "Finally, the pro-proliferative activity of cyclin D1 has also been shown in melanomas in population-based studies, verified through the evaluation of the ki-67 proliferative index." (PMID 33804108, 2021). "Another study reported that CDK4 copy number gain was negatively correlated with anti-PD1 response in all subtypes of advanced melanoma and CCND1 copy number gain was associated with a lack of response to anti-PD-1 therapy in advanced acral melanoma." (PMID 34221994, 2021). "Finally, special attention should be paid to the CCND1/cyclin D1 complex in mucosal melanomas, whose upregulation was strikingly altered." (PMID 33804108, 2021). "A four-probe FISH assay targeting 6p25 (RREB1), 6q23 (MYB), Cep6 (centromere 6), and 11q13 (CCND1) could discriminate between histologically unequivocal melanomas and benign nevi with a sensitivity of 86.7% and specificity of 95.4%." (PMID 34206844, 2021). "KYN decreased the protein level of CDK4 and increased cyclin D1 in melanoma SK-MEL-3 cells." (PMID 34299117, 2021). "A subset of acral and mucosal melanomas may have KIT mutations, in addition to gene amplifications and structural rearrangements, most frequently of the CCND1 gene and SF3B1." (PMID 34571969, 2021). "The combination of CCND1 amplification and CDKN2A loss or CDK4/6 mutations has been associated with resistance mechanisms and shorter progression free survival in patients with BRAF-driven melanoma treated with BRAFi." (PMID 34066022, 2021). "Although our meta-analysis in oral mucosa melanomas is based on a small number of studies, these results justify more experimental studies that increase the scientific evidence on the frequency of alterations of CCND1/cyclin D1 and that ratify its prognostic implications in these type of melanomas." (PMID 33804108, 2021). "Furthermore, immunohistochemical cyclin D1 overexpression strongly predicted a higher Breslow thickness, currently considered the most relevant prognostic factor in individual patients with melanomas." (PMID 33804108, 2021). "Our meta-analysis demonstrates associations between CCND1/cyclin D1 upregulation and some clinicopathological features of melanoma, although no value has been shown in predicting patient survival." (PMID 33804108, 2021).
melanoma (continued). "Factors other than copy number including transcriptional, post-transcriptional and translational regulation may influence cyclin D1 expression in melanoma." (PMID 34225728, 2021). "If confirmed in future studies, cyclin D1 overexpression could be an early event in melanomas due to the activation of oncogenic aberrant upstream pathways (e.g., MAPK, PI3K, and/or WNT canonical)." (PMID 33804108, 2021). "Nuclear cyclin D1 expression was found in all 61 acral melanomas using IHC." (PMID 34225728, 2021). "CCND1/cyclin D1 upregulation could also have specific importance in melanoma context as in the prediction of clinicopathological (e.g., higher Breslow thickness or clinical stage) and/or prognostic (e.g., poor survival) outcomes." (PMID 33804108, 2021). "The CCND1 (BCL1) gene encodes cyclin D1 (also called B-cell lymphoma 1 protein), a key protein for cell cycle regulation (G1/S phase transition), and is also responsible for the BRAFi resistance of melanoma cells." (PMID 32605090, 2020). "For example, the candidate drug target CCND1 is located between the two driver genes in the pathways hsa05200: pathways in cancer, hsa05220: chronic myeloid leukemia, hsa05214: glioma, and hsa05218: melanoma." (PMID 32548109, 2020). "Cyclin D1 amplification (CCND1) is observed in about 15–20% of all BRAF-mutant melanoma." (PMID 32092958, 2020). "Additionally, we were able to show that Cyclin D1 protein, a factor important for G1/S transition, is downregulated in siHuR transfected melanoma cells." (PMID 32455577, 2020). "Therefore, the present study investigated the expression and correlation of cyclin D1 and Ki‐67 at different stages in the stepwise development of invasive melanoma." (PMID 32374893, 2020). "In the melanoma pooled cohort, the median OS was shorter in the CCND1 amplification subgroup." (PMID 32903763, 2020). "CCND1 amplification has been observed in 20–38% of melanoma samples, which indicates that a large group of patients is potentially resistant to BRAFi and could benefit from treatment with a CDK4/6 inhibitor." (PMID 32605090, 2020). "In this context, preclinical studies at our institution have shown that expression of cyclin D1 may confer early invasive properties on melanoma cells." (PMID 32374893, 2020). "In this paper we improved upon and expanded this field of research by identifying that nanomolar concentrations of (Bu2Sn)2TPPS and (Bu3Sn)4TPPS that are sufficient to significantly induce the cell cycle arrest of some melanoma cell lines through the inhibition of cyclin D1 expression." (PMID 31801187, 2019). "Interestingly, we also showed in treated melanoma cells the decreased expression of the protein cyclin D1, a key regulator of the G1/S but also of the G2/M phase transition." (PMID 31801187, 2019). "In addition, one study reported that cyclin D1 contributes to BRAF-inhibitor resistance in cancers such as malignant melanoma, whereas other studies found that cyclin D1 is overexpressed in papillary thyroid carcinoma (PTC)." (PMID 30885146, 2019). "Furthermore, the expression levels of CCNA2, CCNB1, CDK1, and CDK4 decreased in melanoma cells treated with metformin, whereas the levels of p21 and CCND1 increased." (PMID 30754729, 2019). "This appears to support the hypothesis that B-RAF and cyclin D1 control expression of Cks1 and Skp2, which, in turn, mediate degradation of p27 in melanoma cells." (PMID 29423113, 2018). "The rate of overall and c-terminal activating CCND1 mutations in these non-endometrial carcinoma types was rare, at most approximately 1% in melanoma and colorectal carcinoma." (PMID 29969496, 2018). "CCND1 has an oncogene status and substantial evidence exists for its involvement in amplification and overexpression in breast, lung, and oral squamous cell cancers as well as melanomas." (PMID 29464035, 2018).
melanoma (continued). "Moreover, comparison of the porcine results to those reported by human melanoma GWAS indicated shared association signals notably at CDKAL1 and TERT loci but also nearby CCND1, FTO, PLA2G6 and TMEM38B-RAD23B loci." (PMID 29963229, 2018). "The aim of the study was to evaluate any possible correlation between mutations in main growth-controlling genes (BRAF, NRAS, CDKN2A) and copy number variations in frequently amplified candidate genes (MITF, EGFR, CCND1, cMET, and cKIT) during melanoma initiation and progression." (PMID 29492214, 2018). "With exclusion of the CCND1 amplification, which was equally distributed between cell lines from primary and metastatic melanomas [2/8 (25%) vs. 6/24 (25%)], cMET and cKIT amplifications were detected only in cell lines from melanoma metastases." (PMID 29492214, 2018). "E2F1 and Cyclin D1 are highly expressed in melanoma cells and interrelated to each other." (PMID 29108247, 2017). "In conclusion, for the first time we found that RGS4 expression was downregulated in melanoma tissues and cells which inhibited melanoma cell proliferation, migration and invasion due to the inactivation of Cyclin D1 and E2F1 via GPCR-mediated PI3K/AKT pathway." (PMID 29108247, 2017). "Loss of E-cadherin expression, nuclear localization of β-catenin and cyclin D1 expression are characteristics that have been shown to correlate with transformation, increased oncogenic activity and progression of most cancers, including melanoma." (PMID 28056869, 2017). "In V600EBRAF melanoma cells cyclin D1 is constitutively expressed." (PMID 28829835, 2017). "While Perk pro-survival activity is necessary for melanoma genesis and melanoma progression, its ability to antagonize cell division through cyclin D1 supports a model wherein Perk regulation of cell fate is a delicate balance wherein less is not necessarily better." (PMID 27977682, 2016). "Decreased cyclin D1 level might contribute to the observed accumulation of melanoma cells in G0/G1 phase." (PMID 27351373, 2016). "For instance, miRNA-193b suppresses cyclin D1 by binding to its 3′ UTR in melanoma Malme-3M cells." (PMID 27596272, 2016). "Notably, rottlerin suppressed cell growth via the dual inhibition of ERK and NF-κB and downregulation of Cyclin D1 in melanoma cells." (PMID 27626499, 2016). "CCND1 is a target in hepatocellular and pancreatic carcinoma, as well as in melanoma 10,11,14." (PMID 26129688, 2015). "Interestingly, previous reports showed that miR-193b repressed melanoma cell proliferation by directly targeting Cyclin D1." (PMID 25905463, 2015). "CDK4, a cell cycle G1/S kinase, and cyclin D1 (CCND1), were shown to be amplified in melanoma." (PMID 24743024, 2014). "In our series, the significance of the aggressive, ulcerated melanoma being selectively CCND1 positive remains unclear, although it is an additional case supporting Gerami's finding of the aneuploidy correlating with poor prognosis." (PMID 24924836, 2014). "HDAC inhibitors appear to reestablish apoptosis in melanoma cells, induce cell differentiation, and inhibit tumor growth in animal models by down-regulating positive cell cycle regulators such as cyclin D1, c-Myc, C-RAF, and AKT, while inducing the expression of a number of anti-proliferative genes." (PMID 25062770, 2014). "Cyclin D1 is a protooncogene playing an important role in cancer, including melanoma." (PMID 24416617, 2013). "Moreover, Let-7b down-regulated cyclin D1 expression through targeting 3’-UTR of cyclin D1 mRNA, and inhibited cell cycle progression in melanoma cells." (PMID 23806108, 2013).
melanoma (continued). "PRMT5 also did not associate with cyclin D1 in either unsynchronized melanoma cells, or cells harvested in G1 or G2/M phases following double thymidine block (not shown)." (PMID 24098663, 2013). "In addition, an earlier study found positive cyclin D1-nuclei staining in 0.34%, 5%, and 7.75% and positive cyclin D3-nuclei staining in 1.8%, 6.4%, and 17.8% in normal naevi, dysplastic naevi and melanoma biopsy sections, respectively." (PMID 23251804, 2012). "Additionally, there is no genome-wide association study (GWAS) identifying the susceptibility loci of CCND1 for colorectal cancer, although one group recently published a GWAS in which CCND1 was strongly suggestive in melanoma carcinogenesis." (PMID 22606291, 2012). "Cyclin D1 is activated by ATF-2 in proliferating murine melanoma cells." (PMID 21429205, 2011). "Antisense-mediated knockdown of CCND1 triggers apoptosis in vitro and shrinkage of xenografts in mice, suggesting that Cyclin D plays a role in melanoma tumorigenesis and so may be a good target for therapeutic intervention." (PMID 21479172, 2011). "CCND1/ Cyclin D amplification is observed in approximately 4% of melanomas." (PMID 21479172, 2011). "Importantly, FLLL32 was capable of reducing pSTAT3 levels, cyclin D1 expression and inducing apoptosis in primary human melanoma cell cultures derived from recurrent cutaneous melanoma tumors." (PMID 20576164, 2010). "In melanomas, which also harbour BRAFV600E mutations, it has been demonstrated that BRAFV600E activates the MAPK pathway and controls proliferation of melanoma cells through the regulation of cyclin D1 and of the cyclin-dependent kinase inhibitor p27Kip1." (PMID 19878585, 2009). "Therefore, targeting Cyclin D1 may offer an additional therapeutic strategy to suppress cell cycle progression in canine melanoma cells." (PMID 40642276, 2025). "Similarly, the number of cyclin D1+ cells was also increased in YAP1 melanomas." (PMID 38308096, 2024). "Previously, our research group has developed a small molecule inhibitor against Bcl-3 that could directly interfere with Bcl-3-mediated cyclin D1 activity in melanoma resulting in decreased cell proliferation, cell migration, and invasion, as well as decreased tumor growth in vivo." (PMID 39327470, 2024). "It has been found that quercetin induced apoptosis in melanoma cells and destabilized the WNT-FZD-LRP6 complex by suppressing DVL2 and AXIN2, which resulted in decreased β-catenin and the inhibition of the WNT-responsive gene encoding cyclin D1 (CCND1) and cyclooxygenase (COX2)." (PMID 39684513, 2024). "Therefore, cyclin-D1 IHC cannot be used as a surrogate in place of CCND1 FISH in melanomas." (PMID 38247727, 2024). "Notably, our experiments showed the complete rescue of ERK1/2 phosphorylation after DUSP-1 activity inhibition but only a partial recovery of Cyclin D1 expression, suggesting that other unknown mechanisms might be involved in Tfeb silencing of melanoma cells." (PMID 37160873, 2023). "A further study found that cyclin D1 promoter activity is inhibited by 2-cyclopenten-1-one.5-Hydroxymethylfurfural has been reported for its antioxidant and antiproliferative activities in human melanoma A375 cells and has great potential application in cancer chemoprevention." (PMID 37049666, 2023). "To determine whether CCND1 amplification can provide prognostic information for patients with melanoma, regardless of ICIs use, we investigated the association between CCND1 amplification and OS curves using data from the TCGA and MSKCC databases." (PMID 35844619, 2022).